CD163 (CD163 molecule)
Diseases named in the same sentence as CD163 in open-access papers (continued):
Sharing a sentence is not in itself a finding about the gene and the disease.
ischemic stroke (10 papers, 2017 to 2025). A stroke disorder caused by obstruction of blood flow to the brain, due to thrombotic (local blood clot formation) or embolic (due to a blood clot or other material traveling from another site) event. "In the acute stage of an ischemic stroke in rat brains, CD163+PVMs upregulate genes associated with the ECM remodeling, inflammation, and immune response, and downregulate the genes responsible for the inhibition of leukocyte activity." (PMID 40244116, 2025). "In fact, elevated levels of soluble CD163 in the peripheral blood of ischemic stroke patients are negatively associated with lymphocyte counts, and these levels may be involved in the resolution of inflammation by mechanisms that are not yet fully understood." (PMID 34201498, 2021). "However, only the percentage of CD163+/CD16+ events counted 24 h after an ischemic stroke was positively associated with NIHSS score and mRS at admission." (PMID 34201498, 2021). "CD163 is expressed in BAMs in normal conditions, and during inflammation CD163+ BAMs increase vascular permeability to promote leukocyte infiltration in ischemic stroke." (PMID 35844224, 2022). "We examined the subtype-specific distribution of the CD163+ and CD80+ circulating monocytes and evaluated their association with the inflammatory status in 26 ischemic stroke patients and 16 healthy controls." (PMID 34201498, 2021). "To this end, we studied CD163+ macrophages in post-mortem brain tissue of three patients with fatal ischemic stroke deceased 24 h after symptom onset." (PMID 30092836, 2018). "Here we show that an ischemic stroke challenge changes the homeostatic function of CD163+ macrophages by inducing cellular activation of the HIF pathway and generation of VEGF and inflammatory mediators." (PMID 30092836, 2018). "Interestingly, VEGF is detected around CD163+PVMs in human post-mortem brain patients who died 24 h after an ischemic stroke, validating the findings obtained in rats." (PMID 40244116, 2025). "Moreover, other studies using bioinformatics gene analysis have found CD163 as a potential biomarker for unstable atherosclerotic plaque and ischemic stroke." (PMID 38992073, 2024). "Moreover, Sert prevented the hemorrhagic transformation of ischemic stroke as indicated by the notable decrease in neuronal expression of CD163, activity of Heme oxygenase-2 and matrix metalloproteinase-2 and 9 levels." (PMID 37955765, 2023). "The present study was conducted to delineate the CD163 and CD80 profiles in the circulating monocytes of patients after an ischemic stroke and healthy individuals to provide information about their phenotypic distribution and putative function." (PMID 34201498, 2021). "An increased percentage of CD163+/CD16+ and CD163+/CD14++ events was found 24 and 48 h after an ischemic stroke when compared to control subjects (CT)." (PMID 34201498, 2021). "Due to the different subtypes of ischemic stroke and the high variability in lesion volume (detected by CT or NMR imaging), together with the small sample size, we were unable to establish a correlation between CD163+/CD16+ events and these parameters." (PMID 34201498, 2021).
myocarditis (10 papers, 2011 to 2024). Myocarditis is a condition that is characterized by inflammation of the heart muscle (myocardium). "Altogether, these results emphasize the diagnostic utility of illustrating these cells using markers such as CD163 or CD68 in the evaluation of myocarditis." (PMID 39202593, 2024). "The immunohistochemical analysis targeting CD163+ macrophages revealed their representation at approximately one-third of the inflammatory cells in myocarditis." (PMID 39202593, 2024). "Recent research indicates the potential clinical utility of evaluating plasma levels of CD163 in cases of fulminant myocarditis." (PMID 39202593, 2024). "In this study, we identified plasma Siglec-5 and CD163 as novel valuable biomarkers of fulminant myocarditis." (PMID 36428509, 2022). "The hypothesis that death occurred at a later phase of myocarditis is supported by the predominance of CD163+ wound-healing macrophages that colocalized with the T-cells and damaged myocytes at the time of autopsy." (PMID 34956207, 2021). "The abundance of CD163+ macrophages was generally higher in the cardiac tissue of patients with myocarditis, whereas lymphocyte counts were lower in the tissue of patients with SARS-CoV-2 infection vs patients with non–SARS-CoV-2 virus-associated and immune-mediated myocarditis." (PMID 34910083, 2022). "Moreover, CD127 expression was previously reported for mouse intestinal macrophages, human CD68+ synovial macrophages or human CD68+ and CD163+ macrophages in cardiac ventricular tissues sampled from patients with myocarditis, as well as in vitro monocyte-derived human macrophages." (PMID 33717097, 2021). "The dominant role of reparative macrophages in the later phase of DOX-induced myocardial inflammation supports our finding that, after eight weeks of DOX treatment, the expression of the anti-inflammatory macrophage marker CD163 but not CD86 was significantly increased compared to CTRL." (PMID 38247537, 2024).
oral cancer (10 papers, 2014 to 2025). "The infiltration of tumor-associated CD68-positive macrophages and, in particular, tumor-promoting, M2-polarized, CD163-expressing macrophages was shown to be associated with oral cancer initiation and tumor progression." (PMID 35406584, 2022). "It is well known that CD163+ macrophages are associated with oral cancer aggressiveness." (PMID 32842506, 2020). "Furthermore, the expression of CD163 both in macrophages and in cancer cells is associated with poor overall survival and has a significant prognostic impact in oral cancer." (PMID 26769084, 2016). "In the context of oral cancer, CD163+ TAMs can contribute to tumor progression through various mechanisms." (PMID 40297579, 2025). "The expression of the myeloid cell marker CD115, as well as that of the macrophage markers CD68 and CD163, was significantly increased in oral cancer samples compared to healthy oral mucosa." (PMID 35406584, 2022). "Interestingly, loss of RGS12 inhibits the expression of M1 macrophage (CD86) but promotes the expression of M2 macrophage (CD163) in 8-week 4NQO-induced oral cancer tissues." (PMID 36797232, 2023). "Following these findings, our results indicate that CD68 and CD163 may play important roles in carcinogenesis and progression in the patients of oral cancer." (PMID 24883329, 2014). "This hypothesis is also supported by a recent study performed on human TAMs in premalignant oral cancer lesions in which immuno-histochemical analyses lead to the conclusion that tumor infiltrating Th1 cells mediated polarization of CD163+ TAMs toward M1 through IFN secretion." (PMID 30853959, 2019). "CD163+ M2 macrophages and CD57+ natural killer cells were the most promising predictors of survival in oral cancer patients." (PMID 30808992, 2019).
systemic sclerosis (10 papers, 2013 to 2024). A chronic disorder, possibly autoimmune, marked by excessive production of collagen which results in hardening and thickening of body tissues. "In a similar notion, CD163-TWEAK interaction seems to play a role in Systemic Sclerosis pathogenesis, and high sCD163 levels were shown to have a protective role against ulcer development in Systemic Sclerosis patients." (PMID 39451197, 2024). "Another study has reported circulatory macrophage (CD204+CD163+CD206+TLR4+CD80+CD86+) and monocyte (CD14+CD206+CD163+CD204+TLR4+CD80+CD86+) populations that expressed both M1/M2 markers in systemic sclerosis patients and in interstitial lung disease (ILD)." (PMID 35603185, 2022). "Recently, CD14brightCD204+/CD163+M2 macrophages were shown to be increased in the peripheral blood and affected skin of systemic sclerosis (SSc) patients, thus indicating their possible role in the pathogenesis of the disease, as well as in the development of dermal fibrosis." (PMID 27846260, 2016).
adenoma (9 papers, 2020 to 2025). A neoplasm arising from the epithelium. "Numerous crypts were formed inside the enlarged adenomas, in which CD163+ tumor-associated macrophages accumulated." (PMID 34606408, 2021). "Thyroid carcinomas demonstrate high immunogenicity compared to adenomas with extensive infiltration by CD8+, CD68+ and CD163+ macrophages, associated with increased expression of SMAD4 and STAT6 in tumor cells." (PMID 39936166, 2025). "Multiple linear regression analysis showed that in colorectal adenomas measuring ≥ 1 cm, expression of CD163+ and CD86+ TAM was significantly greater than in adenomas <1 cm (P < 0.05), Expression of CD163+ TAM was notably higher in obese patients with CRC." (PMID 41395618, 2025). "Of particular interest is the increased number of CD163+ macrophages in carcinomas compared to adenomas." (PMID 39936166, 2025). "In the CRA group, patients with adenomas ≥1 cm in diameter had higher expression of CD163+ and CD86+ TAMs than those with smaller adenomas (P < 0.05)." (PMID 41395618, 2025). "We found that the number of CD163+ cells in carcinomas was three times higher than in adenomas, confirming the role of these cells in the progression of PCOS." (PMID 39936166, 2025). "Our univariate analysis indicated that patients with adenomas ≥1 cm or multiple adenomas exhibited significantly higher expression of both CD163+ and CD86+ TAMs." (PMID 41395618, 2025). "The number of CD163-labelled M2 macrophages also tended to increase from adenoma to adenocarcinoma." (PMID 33442402, 2021). "CD163 marker was located in the cytoplasms of Monocytes and M2 Macrophages cells, displaying as brown colored granules., and could be slightly expressed in normal mucosa, paracancerous tissue and adenoma tissue." (PMID 36859111, 2023). "CD163-positive cell count in CRC was significantly different from that in normal mucosa, adjacent tissues and adenoma tissues, with statistically significant differences (130.01 ± 45.24 vs. 40.64 ± 15.28, 70.25 ± 33.04, and 85.21 ± 44.69, P < 0.05)." (PMID 36859111, 2023). "Multivariate regression further confirmed this relationship: CD163+ TAMs (β = 7545.441, 95% CI: 5575.552 ~ 9515.329) and CD86+ TAMs (β = 4488.870, 95% CI: 3477.967 ~ 5499.773) were significantly increased in patients with larger adenomas." (PMID 41395618, 2025).
invasive breast carcinoma (9 papers, 2018 to 2024). A carcinoma that infiltrates the breast parenchyma. "CD markers found on the M2 type, CD163, were associated with unfavorable OS, whereas CD markers on the M1 type, CD11c, were correlated with favorable OS in invasive breast cancer." (PMID 32757467, 2020). "Immunofluorescence histo-cytometry of CD163+ TAMs was performed retrospectively on tumor microarrays of 443 cases of invasive breast cancer from patients who subsequently received adjuvant chemotherapy." (PMID 35053472, 2022). "We performed immunofluorescence-based histo-cytometry of CD163+ TAMs on tissue microarrays representing a retrospective cohort of 443 cases of invasive breast cancer from patients who subsequently received adjuvant chemotherapy." (PMID 35053472, 2022). "This study aimed to compare CD163 expression with the widely used CD68 pan-macrophage marker in invasive breast carcinoma." (PMID 32372332, 2020). "Having established that SIGLEC1 is significantly expressed only by Br-TAM, we performed immunofluorescent staining using anti-SIGLEC1 and anti-CD163 antibodies on tissue biopsies from patients with invasive breast cancer and benign lesions." (PMID 30930117, 2019). "Immunohistochemical staining revealed that invasive breast cancer also shows increased phospho-insulin/IGF-1 receptor levels in tumor cells surrounded by CD163+ macrophages." (PMID 29367764, 2018). "To further analyze the clinical impact of S100A7/cPLA2 signaling in modulating the host immunosuppressive response, we investigated the correlation of these two proteins with the abundance of tumor-promoting CD163+ M2-TAMs using TMAs of invasive breast cancer patients." (PMID 35135586, 2022). "The comparison of the scores of stromal immune cells in 30 patients with primary DCIS and its invasive recurrence revealed an increased level of stromal CD20 + lymphocytes B and CD163 + macrophages M2 in invasive breast cancer what is consistent with results reported by other authors." (PMID 34952631, 2021). "The comparison of stromal cells in 30 patients with initial DCIS and its invasive recurrence revealed an increased level of CD20 + immune cells (median score 5% vs. 17%, respectively, p < 0.001) and CD163 + cells (median score 1% vs. 5%, respectively, p < 0.001) in invasive breast cancer." (PMID 34952631, 2021). "Moreover, there are no standardized methods for macrophage detection and different studies have used different markers (e.g., CD68, CD163, or CD206) and staining platforms to make conclusions about the prognostic value of macrophages in invasive breast cancer." (PMID 38720366, 2024). "Furthermore, higher numbers of CD163 and SIGLEC1 single- and double-positive TAMs were reported in invasive breast cancer." (PMID 36358879, 2022).
Lipedema (9 papers, 2020 to 2025). Disorder of adipose tissue characterized by symmetric and bilateral enlargement of the lower extremities due to abnormal deposition of subcutaneous fat often in obese women. "In short, here we identified CD163+ macrophages to be a distinct hallmark of the immune cell composition in lipedema and repolarization of lipedema macrophages is able to normalize the differentiation of adipose-derived stem cells in vitro evaluated by the cellular lipid accumulation." (PMID 36605202, 2022). "Thus, constant exposure of cells to low levels of endotoxins may cause high levels of CD163 in lipedema." (PMID 40149538, 2025). "Adipose tissue-derived stem cells showed increased lipid accumulation compared to controls when differentiated in SVF-derived conditioned media of lipedema patients characterized by high expression levels of CD163." (PMID 40149538, 2025). "We were able to highlight this in a previous study by detecting significantly increased gene expression levels of CD163 within the same lipedema tissue samples." (PMID 37887430, 2023). "Building on these results and using the same cohort, we investigated the M2 macrophage levels using cytometry by time-of-flight and IHC and demonstrated significantly increased numbers of M2/CD163+ macrophages in lipedema compared with the control group." (PMID 37887430, 2023). "To evaluate the functional role of the predominant CD163+ cell population in lipedema we used conditioned medium from lipedema and control SVF, including a treatment with 100 nM IPI-549." (PMID 36605202, 2022). "In conclusion, our results indicate that CD163+ macrophages are a critical component in lipedema and re-polarization of lipedema macrophages can normalize the differentiation of adipose-derived stem cells in vitro evaluated by the cellular lipid accumulation." (PMID 36605202, 2022). "The results obtained in the study point clearly towards a central role of CD163+ immunosuppressive M2 macrophages in lipedema." (PMID 36605202, 2022). "When comparing the marker expression profiles of CD11b+CD64+ cells between lipedema patients and the control group, lipedema patients showed higher levels of CD163, Clever-1, HLA-DR and CD86, and a higher proportion of CD206 expressing cells." (PMID 36605202, 2022). "Upon treatment with IPI-549, the expression of CD163 in lipedema SVF was significantly reduced, nearly to the level of expression in the control group." (PMID 36605202, 2022). "The phenotypic characterization of the immune component of lipedema versus control SVF using CyTOF revealed significantly increased numbers of CD163 macrophages." (PMID 36605202, 2022). "Evaluation of M1 (CD80 and iNOS) and M2 (CD163 and TGFβ) polarization markers using qPCR revealed an increased CD163 expression (3.4-fold increase) in lipedema patients and as such a predominant M2 polarization profile." (PMID 32616854, 2020). "The significantly higher expression of CD163 in subcutaneous fat from lipedema patients compared to BMI-matched controls in other studies further points to increased amounts of M2 macrophages in subcutaneous lipedema fat." (PMID 40149538, 2025). "In lipedema, this inflammatory profile is further amplified by a phenotypic shift from anti-inflammatory M2 (CD163+) macrophages to M1 dominance, which accelerates fibrosis, impairs lymphatic flow, and fosters progressive adipose tissue dysfunction and metabolic deterioration." (PMID 40806207, 2025). "However, as adiponectin levels are either comparable or elevated compared to controls, the relevance of these observations in relation to elevated CD163 levels in M2 macrophages of subcutaneous fat from lipedema patients has yet to be clarified." (PMID 40149538, 2025). "The treatment of the SVF from lipedema patients with IPI-549, a selective phosphatidylinositol-3 kinase γ inhibitor that switches M2 macrophages towards an M1-like phenotype, caused an almost complete downregulation of macrophage CD163." (PMID 40149538, 2025).